EFNA1 (ephrin A1)
Description:
Cell surface GPI-bound ligand for Eph receptors, a family of receptor tyrosine kinases which are crucial for migration, repulsion and adhesion during neuronal, vascular and epithelial development. Binds promiscuously Eph receptors residing on adjacent cells, leading to contact-dependent bidirectional signaling into neighboring cells. Involved in angiogenesis, regulating vascular endothelial cell differentiation and migration through activation of EPHA2. Acts as a ligand for EPHA3, inhibiting epithelial-to-mesenchymal transition of cardiac cells and playing a role in heart development. May also contribute to dendritic spine morphogenesis (By similarity).
Synonyms: LERK-1; EPLG1; LERK1; TNFAIP4; ECKLG; GMAN; B61
Tractability: Antibody: UniProt places it where antibodies can reach, with high confidence; its Gene Ontology location is reachable by antibodies, with high confidence; UniProt predicts a signal peptide or a membrane-spanning region. PROTAC: ubiquitination databases record sites on it; a small molecule that binds it is known.
Gene: Protein-coding gene on chromosome 1 (155,127,876 to 155,134,899, forward strand). Ensembl gene ENSG00000169242.
Subcellular location: Cell membrane; Secreted (Ephrin-A1, secreted form)
Pathways (Reactome):
Developmental Biology: EPH-Ephrin signaling; EPH-ephrin mediated repulsion of cells; EPHA-mediated growth cone collapse
Gene Ontology:
Molecular function: ephrin receptor binding; protein binding; receptor ligand activity
Biological process: ephrin receptor signaling pathway; negative regulation of cell adhesion mediated by integrin; positive regulation of amyloid precursor protein catabolic process; positive regulation of amyloid-beta formation; positive regulation of intracellular signal transduction; protein stabilization; substrate adhesion-dependent cell spreading; aortic valve morphogenesis; axon guidance; endocardial cushion to mesenchymal transition involved in heart valve formation; mitral valve morphogenesis; negative regulation of dendritic spine morphogenesis; negative regulation of epithelial to mesenchymal transition; negative regulation of transcription by RNA polymerase II; regulation of angiogenesis; regulation of blood vessel endothelial cell migration
Cellular component: extracellular region; focal adhesion; plasma membrane; membrane
Genetic constraint (gnomAD): Loss-of-function variants: 8 observed, 24.48 expected, observed/expected ratio (o/e) 0.33, 90% interval 0.19 to 0.59. The upper end of that interval is the gene's LOEUF score, 0.59, which puts it in group 2 of 6, group 1 being the genes least tolerant of losing a copy. Missense variants: 217 observed, 271.99 expected, observed/expected ratio (o/e) 0.8, 90% interval 0.71 to 0.89. Synonymous variants: 89 observed, 105.14 expected, observed/expected ratio (o/e) 0.85, 90% interval 0.71 to 1.01.
Homologues: Orthologues: chimpanzee EFNA1 (100% identical), macaque EFNA1 (98% identical), dog EFNA1 (90% identical), rabbit EFNA1 (89% identical), pig EFNA1 (89% identical), rat Efna1 (86% identical), mouse Efna1 (86% identical), guinea pig EFNA1 (67% identical), tropical clawed frog efna1 (54% identical), zebrafish efna1a (53% identical), zebrafish efna1b (51% identical), Caenorhabditis elegans efn-2 (27% identical), and 4 more. Paralogues in human: EFNA5 (41% identical), EFNA3 (40% identical), EFNA2 (39% identical), EFNA4 (35% identical), EFNB1 (27% identical), EFNB2 (24% identical), EFNB3 (21% identical).
Diseases named in the same sentence as EFNA1 in open-access papers:
EFNA1 is named in the same sentence as 86 diseases in open-access papers, as found by Europe PMC text mining. Sharing a sentence is not in itself a finding about the gene and the disease. The quoted sentences say what the papers report.
breast carcinoma (26 papers, 2010 to 2025). "Here, we use ephrin-A1 knockout mice to examine how ephrin-A1 host deficiency affects cancer growth and metastasis in a murine model of breast cancer." (PMID 32399207, 2020). "Here, we examine how ephrin-A1 host deficiency affects cancer growth and metastasis in a murine model of breast cancer." (PMID 32399207, 2020). "To test the impact of ephrin-A1 host deficiency on cancer progression, we utilized an orthotopic 4T1 mammary tumor model, as well as two different models of metastasis." (PMID 32399207, 2020). "EphA2 is over-expressed in breast cancer cells and its over-expression correlates with decreased EfnA1 expression and loss of estrogen receptor expression." (PMID 28883622, 2017). "Notably, they highlighted that measuring the accompanying ephrins’ expression might have clinical significance by reporting the loss of ephrin-A1 expression in EPHA2-positive breast cancer tissues accompanied by lymph node metastasis." (PMID 35204461, 2022). "EPHA2 activates AMPK signaling via the ligand Ephrin A1-dependent forward pathway to promote the tube-forming and migration ability of endothelial cells, thereby promoting breast cancer metastasis." (PMID 35673569, 2022). "Exosomal EPHA2 transferred from HM breast cancer cells to endothelial cells confers the pro-angiogenic effect by activating AMPK signaling through a ligand Ephrin A1-dependent forward pathway." (PMID 35673569, 2022). "DR-Exos treated with ALW-II-41-27 still exerted profound migratory promoting ability, which indicated that exosomal EphA2 promoted breast cancer migration through EphA2-Ephrin A1 reverse signaling instead of the kinase-related forward signaling." (PMID 33879771, 2021). "Expression analysis of mouse xenograft models and human breast cancer or human Kaposi’s sarcoma demonstrated that ephrin-A1 was widely expressed in tumor parenchyma and tumor endothelium." (PMID 34079823, 2021). "Collectively, our results suggest that exosomal EphA2 derived from drug-resistant cells promotes breast cancer progression through the ERK pathway downstream of EphA2-Ephrin A1 reverse signaling." (PMID 33879771, 2021). "Collectively, these results indicated that exosomal EphA2 promoted breast cancer cell migration and invasion by inducing Ephrin A1 reverse signaling." (PMID 33879771, 2021). "Scholars found out through a series of experiments in metastatic mammary tumor that membrane-tethered Ephrin-A1 can regulates angiogenic responses from initially distant host endothelium." (PMID 34079823, 2021). "In breast cancer model systems, Ephrin-A1 signaling through the EphA2 receptor on the tumor cell can inhibit tumorigenesis, whereas excess unliganded EphA2 promotes tumorigenesis through enhanced proliferation and migration." (PMID 24890385, 2014). "Although we did not observe any significant associations with ephrin ligand expression and clinical outcome, co-expression of EphA2 and ephrin-A1 in Stage I breast cancers correlated with recurrence." (PMID 21935409, 2011). "Lastly, the EPHA2/ephrin-A1 signaling axis in regulating glutamine metabolism in HER2-positive breast cancer has been explored, with findings suggesting that ephrin-A1 loss leads to upregulated glutamine metabolism and lipid accumulation, enhancing tumor growth." (PMID 39408832, 2024). "Deregulated EphA2/Ephrin A1 signal is observed in many types of tumors, particularly breast cancer." (PMID 33879771, 2021). "Moreover, we previously reported that treatment with a neutralizing antibody against soluble forms of ephrin-A1 inhibited primary tumor growth, and another group reported that soluble ephrin-A1 induced cell proliferation in some human breast cancer cell lines." (PMID 33804570, 2021). "Hence, the binding of exosomal EphA2 to Ephrin A1-induced reverse signaling promotes aggressive behavior in breast cancer." (PMID 33879771, 2021).
breast carcinoma (continued). "Moreover, treatment with a fusion protein of monomeric ephrin A1 (mEA1) also induced phosphorylation and degradation of in human breast cancer cells." (PMID 32811512, 2020). "Down regulation of Ephrin A1 in breast cancer increases tumor invasiveness illustrating that this may be a way to maintain EphA2 Ser897 phosphorylation." (PMID 27533087, 2016). "Moreover, HIC1 could function as tumor suppressor in breast cancer through transcriptional repression of ephrin-A1." (PMID 31680974, 2019). "Thus activation of Ephrin-A1 signaling by TGF-β may contribute to the tumor-suppressive effects in ER+ breast cancer." (PMID 24890385, 2014). "We note significant upregulation of genes such as EFNA1, PTMA, SPINT2, and CD24, which have previously been indicated in increased tumor aggression and driving the transition to invasive forms of breast cancer." (PMID 39801521, 2025). "Bioassay studies demonstrated that EFNA1, EFNA3, and EFNA4 expression were higher in breast cancer than in normal tissues, while EFNA5 showed an opposite trend." (PMID 35309935, 2022). "In the UALCAN database, the mRNA expression of EPHA1, EPHA10, EFNA1, EFNA3, and EFNA4 was significantly higher, whereas that of EPHA2, EPHA4, EPHA5, and EFNA5 was significantly lower in breast cancer tissues than in paracancerous tissues." (PMID 33977106, 2021). "Of great interest, ephrin A1 was shown to be released as a soluble monomeric entity by GBM and breast cancer cells." (PMID 32811512, 2020). "In addition, when we divided the 70 breast cancer cell lines into those that had high or low FOXA1 expression, we found that EFNA1 expression was significantly higher in the lines with high FOXA1 expression." (PMID 34202157, 2021). "Exosomal EphA2 activates ERK1/2 signaling through the ligand Ephrin A1-dependent reverse pathway rather than the forward pathway, thereby promoting breast cancer progression." (PMID 33879771, 2021). "Thus, we analyzed co-expression of ephrin-A1, the primary ligand for EphA2, and EphA2 protein in a large Stage I prognostic TMA from the NCI Cooperative Breast Cancer Tissue Resource (CBCTR) Cancer Diagnosis Program (CDP)." (PMID 21935409, 2011). "Moreover, exosomal EphA2 activated ERK1/2 signaling through the ligand Ephrin A1-dependent reverse pathway rather than the forward pathway, thereby promoting breast cancer progression." (PMID 33879771, 2021). "However, our finding that soluble EFNA1 is required for the growth of both a cervical and breast cancer cell line suggests that the positive role of soluble EFNA1 in promoting the growth of cancer cells is not restricted to one cell line or cell type." (PMID 20979646, 2010).
gastric cancer (22 papers, 2012 to 2025). A primary or metastatic malignant neoplasm involving the stomach. "In gastric cancer, high expression level of EFNA1 was found significantly associated with clinical stage, invasion, lymph node metastasis, recurrence and the rs12904 G > A mutation in 3’ UTR increased the susceptibility of the disease." (PMID 37160815, 2023). "A recent case-control study found that genotype frequency of the EFNA1 rs4971066 polymorphism was associated with susceptibility to gastric cancer." (PMID 35309935, 2022). "One study, involving 525 gastric cancer samples and 501 controls, found that rs12904 polymorphism in the EFNA1 gene was strongly associated with gastric cancer risk." (PMID 35309935, 2022). "The result indicated that ephrin-A1 tagSNP rs4971066 GT/TT genotypes was significantly associated with reduced susceptibility of gastric cancer development." (PMID 34079823, 2021). "For the single nucleotide polymorphisms in EFNA1, there are couple papers have demonstrated that rs12904 is a gastric cancer related variant." (PMID 34079823, 2021). "A GWAS research of Asian ethnicity has revealed that ephrin-A1 rs4745 and rs12904 were associated with the risk of gastric cancer." (PMID 34079823, 2021). "EFNA1 rs12904, an miR-200c binding site SNP that shows a strong LD with rs4072037 and is located in the 3’-untranslated region of the EFNA1 gene, can modulate EFNA1 expression and is associated with gastric cancer susceptibility." (PMID 34638981, 2021). "Significant differences were found between the genotype frequencies of EFNA1 rs4971066 polymorphism between gastric cancer patients and healthy controls." (PMID 34079823, 2021). "For instances, a SNP rs12904 in the 3′-UTR of ephrin-A1 was found to be associated with gastric cancer susceptibility." (PMID 34079823, 2021). "Treatment with DS-8895a of EphA2-positive breast and gastric cancer cells was shown to partially inhibit ephrin A1-associated EphA2 phosphorylation." (PMID 32811512, 2020). "GC cells exhibit high amounts of GMAN (gastric cancer metastasis associated long noncoding RNA), a sense lncRNA, which competitively binds to antisense GMAN RNA (GMAN-AS), resulting in polymer formation of the downstream Ephrin A1 mRNA and thus increasing the translation of Ephrin A1 mRNA." (PMID 32754285, 2020). "Single nucleotide polymorphism (SNP) in EFNA1 was important for the progression of gastric cancer, but SNP in this gene may be associated with development of EOC." (PMID 30970615, 2019). "Our previous study revealed that Ephrin A1 was upregulated in gastric cancer and involved in metastasis." (PMID 39838173, 2025). "To investigate the underlying mechanism of how Ephrin A1 induces EMT and metastasis of gastric cancer cells, we employed immunoprecipitation (IP) assay to identify the interactions of Ephrin A1 with the reported EphA receptors." (PMID 39838173, 2025). "Immunohistochemistry staining showed that Ephrin A1 protein levels were positively correlated with the activation status of EGFR in gastric cancer patients." (PMID 39838173, 2025). "Collectively, these data suggest that Ephrin A1 promotes the colonization and metastasis of gastric cancer cells." (PMID 39838173, 2025). "Consistent with our findings, Ephrin A1 expression level was positively correlated with EGFR phosphorylation level in gastric cancer patients." (PMID 39838173, 2025). "Ephrin A1 facilitates colonization and metastasis of gastric cancer cells in vitro and in vivo via inducing epithelial-mesenchymal transition (EMT)." (PMID 39838173, 2025). "Strikingly, mice with Ephrin A1-overexpressing cancer cells developed severe metastatic lesions, while erlotinib treatment strongly reduced the lung metastases of gastric cancer cells." (PMID 39838173, 2025).
gastric cancer (continued). "Although we demonstrated Ephrin A1 functioned as the ligand of EGFR to induce EMT and metastasis in gastric cancer cells in this study, Ephrin A1 was reported to be highly expressed in multiple tumors and EGFR was an important target in many cancers." (PMID 39838173, 2025). "Further multivariate Cox analysis showed that high expression level of Ephrin A1 was an independent positive prognostic factor for predicting outcomes of gastric cancer patients (HR: 2.26; P < 0.05)." (PMID 39838173, 2025). "In this study, our aim is to explore the diagnostic value of serum EFNA1 and MMP13 for gastric cancer." (PMID 38987376, 2024). "Among the queried gastric cancer samples, the samples with changes in EFNA1 accounted for 8%, and the main gene changes were the enhancement of mRNA expression." (PMID 35309935, 2022). "Our study also found that EFNA1 expression was significantly higher in gastric cancer than in normal tissues." (PMID 35309935, 2022). "A microarray analysis combined with basic experiments showed that EFNA1 and GMAN were associated with the invasion ability of gastric cancer cells." (PMID 35309935, 2022). "In a study using RT-PCR to identify the expressions of EPHA2 and EFNA1 in gastric cancer tissues and cell lines compared to normal tissues." (PMID 35309935, 2022). "Another study also showed that EFNA1 knockout in gastric cancer cell lines, reduced its invasion and metastasis in mice." (PMID 35309935, 2022). "In vivo experiments have confirmed that knocking out EFNA1 can weaken the distant metastasis ability of gastric cancer and provide a target for targeted therapy of gastric cancer." (PMID 34399788, 2021). "Knockdown or knockout of GMAN or EFNA1 in gastric cancer cell lines reduces invasive activity and metastases." (PMID 34079823, 2021). "Silencing of C1GALT1 decreased tyrosine phosphorylation of EPHA2, inhibited binding of Ephrin A1 to cell surfaces, and suppressed soluble Ephrin A1-induced migration in gastric cancer cells." (PMID 32005975, 2020). "Notably, EFNA1 has been identified as a novel EGFR ligand that drives epithelial–mesenchymal transition (EMT) in gastric cancer." (PMID 41462698, 2025). "The Ephrin A1/EGFR/EMT regulating axis may provide new strategies for targeting therapy in gastric cancer metastasis." (PMID 39838173, 2025). "Moreover, gastric cancer patients with high Ephrin A1 expression levels or high EGFR phosphorylation levels had poor prognosis compared to low expression group." (PMID 39838173, 2025). "We investigated whether Ephrin A1 facilitated the extravasation ability of gastric cancer cells and subsequent colonization." (PMID 39838173, 2025). "Since cancer cells undergone EMT can acquire invasive phenotypes to initiate metastatic dissemination, so we evaluated whether Ephrin A1 induced the invasive phenotypes of gastric cancer cells." (PMID 39838173, 2025). "Together, these results suggest that Ephrin A1 may induce EMT of gastric cancer cells through activating EGFR signaling." (PMID 39838173, 2025). "Ephrin A1 has been reported to play crucial roles in many cancers, including gastric cancer." (PMID 39838173, 2025). "Here, we report Ephrin A1 as a novel ligand of EGFR in gastric cancer." (PMID 39838173, 2025). "To determine whether EGFR signaling mediates the function of Ephrin A1 in regulating EMT of gastric cancer cells, we generated an EGFR knockout cell line by CRISPR-Cas9 system in MKN45 cells." (PMID 39838173, 2025). "To further explore the underlying mechanism of how Ephrin A1 induces EMT and metastasis of gastric cancer cells, we hypothesize whether Ephrin A1 interacts with other important tyrosine kinase receptors, such as EGFR, FGFR and integrins." (PMID 39838173, 2025). "LncRNA GMAN, overexpressed in gastric cancer, regulates ephrin A1 mRNA translation through competitive binding with GMAN-As, thus promoting proliferation and metastasis in gastric cancer." (PMID 34888249, 2021).